GRHL2 (grainyhead like transcription factor 2)
Diseases named in the same sentence as GRHL2 in open-access papers (continued):
Sharing a sentence is not in itself a finding about the gene and the disease.
keloid (1 paper, 2024). An irregularly shaped, elevated mark on the skin caused by deposits of excessive amounts of collagen during wound healing. "Considering the elevated levels of TGF-β in keloid tissue, as well as its inhibitory effect on GRHL2 expression, we cannot conclusively determine that the loss of GRHL2 is the cause of keloid formation." (PMID 39402063, 2024). "In our research, we have also confirmed a decrease of GRHL2 expression in EMT keratinocytes from keloids." (PMID 39402063, 2024). "We also examined surgically excised keloid samples and observed EMT in the epidermal component of keloids, along with a downregulation of GRHL2 expression." (PMID 39402063, 2024). "However, further research is needed to determine whether the decreased expression of GRHL2 in keloid keratinocytes can enhance the regulation of cellular EMT by IL-17." (PMID 39402063, 2024). "In addition, GRHL2 is downregulated in keloids tissue, a type of abnormal hypertrophic scar." (PMID 39402063, 2024). "Moreover, the reduction of GRHL2 expression can affect the TGF-β, TNF-NFκB, and IL-6 signaling pathways of keratinocytes, thereby potentially influencing their interaction with the keloid microenvironment." (PMID 39402063, 2024).
liver disease (1 paper, 2020). "For example, GRHL2 potently exacerbated liver injury and fibrosis by inhibiting miR‐122 expression in ethanol‐induced liver disease." (PMID 32324317, 2020). "Various researches have widely identified the role of GRHL2 in liver diseases." (PMID 32324317, 2020).
liver failure (1 paper, 2025). A liver disease characterized by the liver losing or has lost all of its function. "First, we found that GRHL2 expression was induced in patients with liver failure both at the mRNA and protein levels." (PMID 41385584, 2025). "Compared to control samples, GRHL2 expression was induced in ALD-related liver failure (log2 FC = 1.38, q-value = 0.11), which correlated with the induction of genes defined as up-regulated during HCT as well as genes from the Epith-Signature." (PMID 41385584, 2025). "Finally, GRHL2 immunostaining in samples from patients with liver failure due to primary biliary cholangitis (PBC) or PSC also revealed GRHL2-positive hepatocytes." (PMID 41385584, 2025).
liver fibrosis (1 paper, 2020). "Collectively, GRHL2 played a contributory role in NAFLD by exacerbating liver fibrosis and intestinal mucosal barrier dysfunction with the involvement of miR‐200‐dependent SIRT1 and the MAPK signalling pathway." (PMID 32324317, 2020). "Meanwhile, GRHL2 knockdown ameliorated liver fibrosis and intestinal mucosal barrier dysfunction by inactivating MAPK signalling pathway in NAFLD mice." (PMID 32324317, 2020). "Taken together, GRHL2 promoted liver fibrosis and intestinal mucosal barrier dysfunction in NAFLD mice through activation of MAPK signalling pathway." (PMID 32324317, 2020). "In this study, we identified the functions of GRHL2 in NAFLD and further found that SIRT1 down‐regulation induced by GRHL2‐dependent miR‐200 or MAPK signalling pathway activated by GRHL2 exacerbated liver fibrosis and intestinal mucosal barrier dysfunction in NAFLD." (PMID 32324317, 2020). "Last but not least, the present study validated that GRHL2 activated MAPK signalling pathway and exacerbated liver fibrosis and intestinal mucosal barrier dysfunction in NAFLD mice." (PMID 32324317, 2020).
lung squamous cell carcinoma (1 paper, 2025). "This study delineates a comprehensive landscape of 3447 lung squamous cell carcinoma (LUSC)‐specific oncogenic enhancers (SOEs), unveiling their pivotal role in driving tumor pathogenesis through enrichment of key transcription factors, including SOX2, p63, KLF5, and GRHL2." (PMID 40899632, 2025).
metastatic colorectal cancer (1 paper, 2021). "Here, we found that GRHL2, ELF3, and OVOL1 were overexpressed in the CTC lines compared with SW620 cells (metastatic colorectal cancer cell line), particularly GRHL2." (PMID 34771571, 2021).
Nail dystrophy (1 paper, 2020). Onychodystrophy (nail dystrophy) refers to nail changes apart from changes of the color (nail dyschromia) and involves partial or complete disruption of the various keratinous layers of the nail plate. "Among the top associations, we recapitulated previously known, such as "SRD5A3—Abnormal full-field electroretinogram—recessive" and "GRHL2 –Nail dystrophy—recessive", and discovered one potentially novel, “RRAGA–Abnormality of the skin—dominant”." (PMID 32271766, 2020). "We applied Phenogenon to the Phenopolis exome dataset and were able to recapitulate known gene-phenotype relations, such as "SRD5A3—Abnormal full-field electroretinogram—recessive" and "GRHL2 –Nail dystrophy—recessive"." (PMID 32271766, 2020).
non-melanoma skin carcinoma (1 paper, 2024). "Therefore, GRHL2 may have a dual role in the development of non-melanoma skin cancers." (PMID 39402063, 2024).
periodontitis (1 paper, 2021). An acute or chronic inflammatory process that affects the tissues that surround and support the teeth. "Grhl2 cKO suppressed the expression of junction proteins at the junctional epithelium and promoted the progression of alveolar bone loss in the ligature-induced periodontitis model." (PMID 34445604, 2021). "Recent studies have indicated the unique roles of Grainyhead-like (Grhl) family genes in the regulation of epithelial barrier functions, and periodontitis was induced in Grhl2 conditional knockout (cKO) mice using a 5-0 silk ligature." (PMID 34445604, 2021).
prostate adenocarcinoma (1 paper, 2019). "When we compared these t-SCNC cases with the prostate adenocarcinoma cases, we observed different accessibilities for the TFs AR, HOXB13, NKX3-1, and GRHL2." (PMID 31604930, 2019).
prostate tumor (1 paper, 2019). "AR, FOXA1, and GRHL2 (a co-regulator of AR) are key TFs that promote prostate tumor progression." (PMID 31515496, 2019).
sensory impairment (1 paper, 2020). "GRHL2 might influence the susceptibility to ARHI and DFNA28.22, 24 Just like ARHI and DFNA28, NIHL is one type of sensory impairment." (PMID 30853467, 2020).
small cell lung carcinoma (1 paper, 2021). Small cell lung cancer (SCLC) is a highly aggressive malignant neoplasm, accounting for 10-15% of lung cancer cases, characterized byrapid growth, and early metastasis. "Studies have reported that patients with high GRHL2 expression are associated with a poor prognosis in small-cell lung cancer." (PMID 33810548, 2021).
somatotropinoma (1 paper, 2020). "Our data indicated that three genes having pronounced effects on tumorigenesis were strongly downregulated by SSA/DA in somatotropinoma tissues (MUC16, MACC1, and GRHL2) and confirmed these findings in functional GH3 cell experiments." (PMID 33680922, 2020).
tongue tumor (1 paper, 2018). "We also surveyed the level of p-Erk1/2 and p-JNK in the tongue tumor tissues in Grhl2 WT and KO mice exposed to 4-NQO." (PMID 29735981, 2018). "However, Grhl2 KO completely abolished the tongue tumor formation after chronic exposure to the chemical carcinogen 4-nitroquinoline 1-oxide (4-NQO), which led to rampant tongue cancer development in the wild-type (WT) mice." (PMID 29735981, 2018). "Likewise, the expression of GRHL2 target proteins, e.g., Oct-4 and p63, were readily detectable in Grhl2 WT tongue tumor but were significantly suppressed in Grhl2 KO tissues even exposed to 4-NQO for 4 months." (PMID 29735981, 2018).
tumor (82 papers, 2009 to 2026). "To investigate the mechanism by which EMT keratinocytes restore their epithelial state during wound healing, we focused on the MET-regulated factor GRHL2, which has been implicated in tumor cells." (PMID 39402063, 2024). "This resulted in reduced primary tumor growth and a reduction in number and size of lung colonies, indicating that growth suppression was the predominant consequence of GRHL2 loss." (PMID 36768838, 2023). "On the other hand, GRHL2 protein expression was positively associated with higher tumor grade, larger tumor size and higher risk of disease relapse." (PMID 35269877, 2022). "On one hand, GRHL2 mRNA expression was reduced in tumor samples, and lower GRHL2 levels were associated with significantly better survival, indicative of its tumor suppressor role." (PMID 35269877, 2022). "Grainyhead-like 2 (Grhl2), a transcription factor, has been reported to be associated with several tumor processes including EMT." (PMID 28067907, 2017). "EOC tumours with lower GRHL2 levels are associated with the Mes/Mesenchymal molecular subtype and a poorer overall survival." (PMID 26887977, 2016). "Our data also indicate that down-regulation of Grhl2 expression during tumor progression contributes to loss of epithelial phenotype and epithelial-to-mesenchymal transition." (PMID 23284647, 2012). "Similarly, the significant association between radiosensitivity and GRHL2 expression was specifically exited in tumor cell lines of CNS origin instead of other tissue origins." (PMID 37062025, 2023). "In fact, a similar function may also be involved in the many examples where GRHL2 is positively associated with tumor progression and metastasis." (PMID 36691073, 2023). "Out of these, GRHL2 has been widely associated with neoplastic diseases." (PMID 34868979, 2021). "Oncogene GRHL2 is a transcriptional controller of proliferation and differentiation in epithelial cells, both during progression and tumor development, but this gene might be linked with proliferation of pituitary prolactinoma cells." (PMID 33709028, 2021). "We observe that gain of GRHL2 activity through loss of enhancer methylation with following increase in proliferation‐related genes is characteristic of non‐responders, suggesting that non‐responding tumor cells can gain proliferative potential during treatment stress." (PMID 38671580, 2024). "Moreover, through computational modeling, the same study has predicted that GRHL2 promotes the association of hybrid E/M phenotype with high-tumor initiating stem-like traits, which might be helpful in stratifying patients with higher metastatic risk." (PMID 32974388, 2020). "In addition, our computational model predicts that GRHL2 can also associate hybrid E/M phenotype with high tumor-initiating potential, a prediction strengthened by the observation that the higher levels of these PSFs may be predictive of poor patient outcome." (PMID 27008704, 2016). "Our data showed that Grhl2 was the only transcription factor that had such an extraordinary correlation with E-cadherin expression, and multiple functional assays confirmed that changes of epithelial gene expressions were strongly associated with Grhl2 expression during tumor progression." (PMID 23284647, 2012). "Numerous studies on GRHL2 mRNA or protein expression showed upregulation or downregulation of GRHL2 in a large variety of human cancers, possibly reflecting both tumor-suppressive and oncogenic functions of the GRHL2 transcription factor." (PMID 40889682, 2025). "Despite clear evidence of the tumor-suppressive role of GRHL2, it also has been reported to exhibit protumorigenic functions." (PMID 40889682, 2025). "The expression levels of genes ESRP1, GRHL2, MTHFD2, RACGAP1, and SQLE, considered risk factors, were significantly up‐regulated in tumor tissues compared with normal tissues and were statistically significantly associated with a poor prognosis." (PMID 40586163, 2025).
tumor (continued). "The developmental transcription factor grainyhead-like 2 (GRHL2) has been attributed both tumor-suppressive and protumorigenic functions in a large variety of human cancers." (PMID 40889682, 2025). "GRHL2 plays a dynamic role with tumor-suppressive and oncogenic functions in a context-dependent manner." (PMID 39199676, 2024). "GRHL2 was previously shown to support NK cell-mediated tumor cytotoxicity through a mechanism involving epigenetic stimulation of ICAM-1 expression, which supported enhanced NK-target cell synapse formation." (PMID 38706844, 2024). "Together, these results suggest that the tumor suppressor activity of miR-6794-3p is exerted via the ability of RBBP4 inhibition to upregulate GRHL2." (PMID 39430246, 2024). "The potential influence of GRHL2 on the tumor immune response and regulation of programmed death-ligand 1 (PD-L1) warrants investigation." (PMID 39199676, 2024). "This points to the established notion that GRHL2 behaves as a tumor suppressor in various cancers and regulates tumor progression by inhibition of EMT." (PMID 39199676, 2024). "Each of these phenotypes jointly articulate stem cell-like enrichment and plasticity imparted by elevated GRHL2 levels in an ER-positive breast cancer cell to perpetuate tumor progression." (PMID 39199676, 2024). "We also observed an increase in dormancy markers NR2F1 and CDKN1B and a slowing of proliferation and tumor growth in vivo with GRHL2 overexpression." (PMID 39199676, 2024). "At high levels, GRHL2 begins to regulate transcription of genes associated with dormancy, stemness, and EMT plasticity, highlighting a pleiotropic role in tumor progression." (PMID 39199676, 2024). "We observed that around an expression level of 6 RSEM, there appeared to be a bimodal distribution of GRHL2 expression, possibly reflecting the tumor types that are either epithelial (GRHL2 high) or mesenchymal (GRHL2 low)." (PMID 37761927, 2023). "GRHL2 has been shown to act as a tumor metastasis suppressor, by opposing epithelial-mesenchymal transition (EMT) through upregulation of epithelial markers or downregulation of mesenchymal markers." (PMID 36768838, 2023). "GRHL2 expression appears to support cancer growth and even disease progression in most tumor types investigated." (PMID 36691073, 2023). "Conversely, tumour cells in the mesenchymal state possessed low expression levels of GRHL2 and OVOL1, high expression levels of ZEB1 and SNAI2." (PMID 36808651, 2023). "Tumour cells in a hybrid E/M state possessed moderated expression levels of GRHL2, OVOL1, ZEB1 and SNAI2." (PMID 36808651, 2023). "We therefore analyzed patient tumor GRHL2 expression data from The Cancer Genome Atlas with respect to the reported aneuploidy score for those tumors." (PMID 37761927, 2023). "The tumour cells in the epithelial state possessed elevated expression levels of GRHL2 and OVOL1, low expression levels of ZEB1 and SNAI2." (PMID 36808651, 2023). "Tumor-promoting roles of GRHL2 in oral squamous cell carcinoma (OSCC), esophageal, pancreatic and colorectal cancer (CRC), as well as similar roles of GRHL3 in CRC, have been summarized in a recent review." (PMID 35269877, 2022). "Tumor cells with GATA3 or GRHL2 positive nuclei also contain the pRCC marker cytokeratin 7 (CK7) in the cytoplasm, without any traces of AQP1." (PMID 35013217, 2022). "GRHL2 is also known to function in cancer, both as an oncogene, but also as a potential tumour-suppressor gene, through inhibition of the epithelial-mesenchymal transition (EMT)." (PMID 35269877, 2022). "The roles of GRHL2 in tumour pathogenesis seem to be complex and controversial, varying with cancer type." (PMID 34868979, 2021). "GRHL2 usually acted as a tumor suppressor due to inhibiting migration and invasion in several types of cancer; also, GRHL1 suppresses SCC." (PMID 34888136, 2021).
tumor (continued). "For example, several genes linked to RA credible SNPs in FLS were implicated in cell proliferation and tumor development (e.g., SPRED2, GRHL2, CDK6, RUNX1, and ZFP36L)." (PMID 34433485, 2021). "The tumor suppressive role of GRHL2 is largely mediated though the suppression of EMT which is summarized in the following section." (PMID 32974388, 2020). "The mechanisms of regulation of tumor progressioncontrolled by GRHL2 are very diverse and obviously depend on tissue type.Moreover, this transcription factor has conflicting effects: it can contributeto tumor progression or suppress tumor growth." (PMID 33173593, 2020). "In the 4T1 tumor model, GRHL2 was found to be significantly downregulated in cells that had undergone EMT." (PMID 31084623, 2019). "Copy losses were also commonly observed for key tumor suppressors relevant to mCRPC biology, including GRHL2, ZFHX3, FGFR2, NCOR1, PHLPP1, and BRCA1." (PMID 31136607, 2019). "After 16 weeks of 4-NQO treatment, Grhl2 WT mice exhibited gross tumor nodule formation on the tongue, while Grhl2 KO mice (Tmx1) displayed complete absence of tumor nodule formation." (PMID 29735981, 2018). "In light of primary tumor development, this relationship between GRHL2 and TGF-β signaling further supports the pro-carcinogenic effects of GRHL2 that have been reported by several laboratories, including ours." (PMID 29735981, 2018). "Our current finding using the Grhl2 cKO model is the first genetic evidence to support the role of GRHL2 in primary tumor development from normal oral epithelia." (PMID 29735981, 2018). "When exposed to 4-nitroquinoline 1-oxide (4-NQO), a strong chemical carcinogen, Grhl2 wild-type (WT) mice developed rampant oral tongue tumors, while Grhl2 KO mice completely abolished tumor development." (PMID 29735981, 2018). "GRHL2 is highly expressed in liver metastases of PDAC (7/7: 100%, high group), and notably, GRHL2 expression in liver metastasis is significantly higher than in paired primary tumor obtained from the same PDAC patient (n = 7) (P = 0.017; chi‐square test)." (PMID 28960866, 2017). "In our previous study, we have proved that Grhl2 inhibits proliferation and promotes apoptosis so that it functioned as a tumor suppressor." (PMID 28067907, 2017). "In an independent EOC collection (JPKO, GSE30311), the median mRNA level of GRHL2 in Mes tumours was also significantly lower, as validated by RT-qPCR." (PMID 26887977, 2016). "The single variable analyses of distant metastasis-free survival (DMFS) for GRHL2 and four clinical prognostic factors (ER status, lymph node status, tumor size and tumor grade) are significant (log-rank tested p<0.05)." (PMID 23441166, 2013). "Cieply et. al., however, reported Grhl2 downregulated specifically in the tumor initiating cells compared with other tumors." (PMID 23441166, 2013). "Using 4T1 cell line, the miR-155 promotes macroscopic tumor formation in the lung with a significantly upregulation of Grhl2." (PMID 23441166, 2013). "Using the 4T1 tumor model, we found Grhl2 to be significantly down-regulated in disseminated cancer cells that had undergone EMT." (PMID 23284647, 2012). "Data from mouse models show that over-expression of Grhl2 promotes epithelial gene expression and promotes tumor progression." (PMID 23284647, 2012). "Our results showed that over-expression of Grhl2 significantly promoted tumor growth and metastasis." (PMID 23284647, 2012). "Surprisingly, these data also show that stable expression of Grhl2 promotes tumor growth and metastasis." (PMID 23284647, 2012). "Our data show that Grhl2 promotes epithelial gene expression and also promotes tumor growth and metastasis." (PMID 23284647, 2012). "Next, we tested if over-expression of Grhl2 was able to inhibit EMT during tumor progression and block tumor metastasis." (PMID 23284647, 2012).